ZKSCAN3 (zinc finger with KRAB and SCAN domains 3)
Diseases named in the same sentence as ZKSCAN3 in open-access papers (continued):
Sharing a sentence is not in itself a finding about the gene and the disease.
prostate carcinoma (7 papers, 2016 to 2025). A carcinoma that arises from epithelial cells of the prostate gland. "Further analyses in radical prostatectomy specimens and prostate cancer cell lines indicated that ZKSCAN3 overexpression was associated with tumor outgrowth." (PMID 32824199, 2020). "Furthermore, ZKSCAN3 expression is directly associated with shorter OS, relapse-free survival, and an unfavorable prognosis in prostate cancer, gastric carcinoma, and HCC." (PMID 39519085, 2024). "In addition, epidemiological studies have suggested that ZKSCAN3 may be involved in the regulation of prostate cancer risk after vasectomy, but its specific mechanism still needs to be explored in depth." (PMID 40723888, 2025). "The genomic amplification-driven and multi-targeted transcriptional regulation pattern of ZKSCAN3 revealed in cervical cancer provides new perspectives to explore its cross-organ oncogenic mechanism in prostate cancer." (PMID 40723888, 2025). "ZKSCAN3 drives the malignant phenotype through a multifaceted regulatory network in prostate cancer." (PMID 40723888, 2025). "In human malignancies, such as colon and prostate cancer, ZKSCAN3 functions as an oncogenic transcription factor." (PMID 39519085, 2024). "In breast, bladder, and prostate cancer models, ZKSCAN3 has demonstrated an enhancing effect on cancer cell vitality, migration, invasiveness, and tumorigenicity." (PMID 39519085, 2024). "In prostate cancer cell lines, ZKSCAN3-shRNA significantly reduces colony formation, cell viability, invasion, migration, and the expression of MMP2 and MMP9 while inducing apoptosis." (PMID 39519085, 2024). "Zinc finger protein with KRAB and SCAN domains 3 (ZKSCAN3) acts as an oncogenic transcription factor in human malignant tumors, including colon and prostate cancer." (PMID 36012568, 2022). "In prostate cancer lines, ZKSCAN3 silencing resulted in significant decreases in cell proliferation/migration/invasion." (PMID 32824199, 2020). "We thus decided to further investigate the function of ZKSCAN3 in prostate cancer, using surgical specimens as well as human cell lines." (PMID 32824199, 2020). "One of the molecules identified by DNA microarray (i.e., ZKSCAN3) was then assessed in radical prostatectomy specimens and human prostate cancer lines." (PMID 32824199, 2020). "Specifically, in prostate cancer, ZKSCAN3 has been shown to modulate the cell cycle as well as cell attachment, migration, and motility." (PMID 32824199, 2020). "To determine the impact of ZKSCAN3 on tumor progression, we first examined its expression in 5 human prostate cancer lines." (PMID 32824199, 2020). "While the pro-invasive and microenvironmental remodeling mechanisms established by ZKSCAN3 in prostate cancer demonstrate its conserved function as a cancer driver, its unique mode of action in pancreatic cancer reveals the complexity of tissue-specific regulation." (PMID 40723888, 2025). "In prostate cancer, ZKSCAN3 regulates cell cycle progression, attachment, migration, and motility." (PMID 39519085, 2024). "Consistent with previous observations, we demonstrated that ZKSCAN3 silencing in prostate cancer lines resulted in significant reduction of cell viability, colony formation, cell migration, cell invasion, and the expression of MMP2/MMP9, as well as significant induction of apoptosis." (PMID 32824199, 2020). "Furthermore, ZKSCAN3 was suggested to play an important role in the development and progression of prostate cancer." (PMID 32824199, 2020). "Additionally, using a prostate cancer line, ZKSCAN3 overexpression was shown to enhance cell detachment, cell migration, and tumorigenicity in xenograft-bearing mice and reduce apoptosis." (PMID 27447553, 2016). "Vasectomy significantly induced ZKSCAN3 expression in prostate tissues from C57BL/6 mice and prostate cancers from TRAMP mice." (PMID 32824199, 2020).
prostate carcinoma (continued). "Meanwhile, using immunostaining in a commercially available tissue microarray, none of 2 normal prostate tissues versus 49% (38/78) of prostate cancers were found to strongly express ZKSCAN3." (PMID 32824199, 2020). "Our immunohistochemistry in surgical specimens further showed that ZKSCAN3 expression was elevated in prostate cancer, compared with HGPIN, and in HGPIN, compared with non-neoplastic prostate tissue." (PMID 32824199, 2020). "Third, ZKSCAN3 protein overexpression was observed in none of normal prostate tissues versus 49% of prostate cancer specimens, while ZKSCAN3 gene amplification was detected in none of primary tumors, 20% of lymph node metastases, and 26% of bone metastases." (PMID 27447553, 2016). "Moreover, ZKSCAN3 gene amplification was detected in none of 12 primary prostate cancers versus 20% (1/5) of lymph node metastases or 26% (5/19) of bone metastases." (PMID 32824199, 2020). "Immunohistochemistry showed increased ZKSCAN3 expression in adenocarcinoma vs. prostatic intraepithelial neoplasia (PIN), PIN vs. non-neoplastic prostate, Grade Group ≥3 vs. ≤2 tumors, pT3 vs. pT2 tumors, pN1 vs. pN0 tumors, and prostate cancer from patients with a history of vasectomy." (PMID 32824199, 2020). "Upon DNA microarray screening, we revealed that vasectomy considerably induced the expression of ZKSCAN3, a family member of the KRAB and SCAN domain-containing zinc-finger transcription factors, in both non-neoplastic prostate and prostate cancer." (PMID 32824199, 2020). "Of these, the expression of ZKSCAN3 was indeed significantly up-regulated in non-neoplastic prostate tissues from 24-week-old C57BL/6 mice undergoing vasectomy at 10 weeks and in prostate cancers from 24-week-old TRAMP mice undergoing vasectomy at 4 weeks." (PMID 32824199, 2020).
colon cancer (6 papers, 2016 to 2025). "In this study, we investigated the molecular mechanisms and pathways underlying colon cancer development mediated by ZKSCAN3 in relation to the oncogenic WNT pathway, because ZKSCAN3 and WNT/β-catenin pathways are well known in colon carcinogenesis." (PMID 36012568, 2022). "Therefore, ZKSCAN3 deficiency suppressed cell cycle progression in HCT116 colon cancer cells by delaying mitosis progression from prometaphase to telophase." (PMID 36012568, 2022). "The results revealed that ZKSCAN3 is a core transcription factor driving the specific expression of CtOATP1B3 colon cancer." (PMID 40723888, 2025). "ZKSCAN3 has emerged as a pivotal factor in promoting the growth of colon cancer cells, both in vitro and in vivo, through an orthotopic tumor model." (PMID 39519085, 2024). "We identified ZKSCAN3 as a downstream target of the WNT/β-catenin/TCF signaling pathway in colon cancer." (PMID 36012568, 2022). "qPCR and promoter assays using PNU and MSAB confirmed that ZKSCAN3 was transcriptionally regulated through the WNT/β-catenin/TCF signaling pathways in colon cancer cells." (PMID 36012568, 2022). "In colon cancer cell lines, down-regulation of ZKSCAN3 via its shRNA or siRNA and its enforced expression inhibited and induced, respectively, colony formation as well as tumorigenicity and progression of xenografted tumors in mice." (PMID 27447553, 2016). "Furthermore, the upregulation of ZKSCAN3 increases the expression of colon cancer progression factors such as cyclin D1, epidermal growth factor receptor, integrin β4, and vascular endothelial growth factor." (PMID 36012568, 2022). "In addition, ZKSCAN3 upregulation by oncogenic WNT/β-catenin signaling is an early event of the adenoma–carcinoma sequence in colon cancer development." (PMID 36012568, 2022). "In conclusion, ZKSCAN3 could be responsible for WNT/β-catenin-induced chromosomal instability in colon cancer cells through the suppression of MAD2L2 expression." (PMID 36012568, 2022). "Moreover, ZKSCAN3 knockdown in colon cancer cell lines resulted in impaired anchorage-independent growth and orthotopic tumor growth, whereas overexpression of ZKSCAN3 showed the opposite effect and increased 5-fluorouracil resistance." (PMID 30241382, 2018). "Furthermore, the overabundance of ZKSCAN3 correlates with elevated levels of several factors that contribute to colon cancer progression, including integrin, cyclin D1 (CCND1), epidermal growth factor receptor (EGFR), and vascular endothelial growth factor (VEGF)." (PMID 39519085, 2024). "Therefore, we determined whether β-catenin-dependent ZKSCAN3 upregulation is observed in the early precursor lesions of colon cancer as well as in advanced cancers." (PMID 36012568, 2022). "Therefore, ZKSCAN3 upregulation occurred in the early stages of colon cancer development." (PMID 36012568, 2022). "Furthermore, ZKSCAN3 upregulation suppressed the expression of the mitotic spindle checkpoint protein, Mitotic Arrest Deficient 2 Like 2 (MAD2L2) by inhibiting its promoter activity and eventually inducing chromosomal instability in colon cancer cells." (PMID 36012568, 2022). "Therefore, ZKSCAN3 could play a role, such as in disturbing chromosomal stability, in carcinogenic processes at the early stage of the adenoma-carcinoma sequence, considering that dysregulated WNT/β-catenin is the main and early driver of colon cancers." (PMID 36012568, 2022).
hepatocellular carcinoma (6 papers, 2021 to 2025). A malignant tumor that arises from hepatocytes. "The multidimensional regulatory mechanisms of ZKSCAN3 in hepatocellular carcinoma are gradually being revealed." (PMID 40723888, 2025). "The multilevel oncogenic mechanism of ZKSCAN3 in hepatocellular carcinoma provides important clues to analyze its functional commonality and specificity in other digestive tract tumors." (PMID 40723888, 2025). "At the level of epigenetic regulation, the microRNA miR-124 antagonizes the promotion of EMT by targeting and inhibiting ZKSCAN3 expression, thereby maintaining epithelial cell integrity and inhibiting hepatocellular carcinoma metastasis." (PMID 40723888, 2025). "CHD1L had the ability to bind to the promoter of ZKSCAN3, inhibiting its transcription and stimulating the hepatocellular carcinoma migration." (PMID 37033447, 2023). "For a 5-year survival rate, ZKSCAN3 is used for the potential prognostic marker of hepatocellular carcinoma patients." (PMID 35038288, 2022). "Moreover, ZKSCAN3 is also overexpressed in hepatocellular carcinoma tissues and promotes hepatocellular carcinoma migration and invasion." (PMID 37175493, 2023). "In addition, the oncogenic protein CHD1L inhibits the transcriptional activity of ZKSCAN3 by binding to it and enhances the migration of hepatocellular carcinoma cells by promoting the degradation of focal adhesion protein (Paxillin) and regulating focal adhesion (FA) dynamics." (PMID 40723888, 2025). "Additionally, in hepatocellular carcinoma (HCC), ZKSCAN3 stimulates ITGβ4 expression by binding to its promoter, enhancing AKT phosphorylation, and triggering a signaling cascade essential for EMT." (PMID 39519085, 2024). "Furthermore, in hepatocellular carcinoma (HCC), ZKSCAN3 facilitates epithelial-mesenchymal transition (EMT), as evidenced by changes in the expression patterns of EMT markers, including decreased E-cadherin and increased N-cadherin and vimentin levels." (PMID 39519085, 2024).
breast carcinoma (5 papers, 2020 to 2025). "Although the molecular details of its action network still need to be deeply analyzed, the available evidence has highlighted the potential value of ZKSCAN3 as a therapeutic target in breast cancer." (PMID 40723888, 2025). "The dual regulatory properties and synergistic effects across signaling pathways exhibited by ZKSCAN3 in breast cancer provide important insights to reveal its functional diversity in other solid tumors." (PMID 40723888, 2025). "Studies have shown that ZKSCAN3 promotes the proliferation, migration, and invasive ability of breast cancer cells (e.g., MCF-7, MDA-MB-231) by regulating cell cycle and apoptosis-related molecular networks." (PMID 40723888, 2025). "ZKSCAN3 exhibits significant pro-oncogenic properties in breast cancer, and its high expression synergistically drives malignant progression through multiple signaling pathways." (PMID 40723888, 2025). "Specifically, in breast cancer, ZKSCAN3 expression exhibits a positive correlation with CCND1 and BCL2 expression, while it negatively correlates with the expression of Bcl2 Associated X Protein (Bax)." (PMID 39519085, 2024). "In breast cancer cells, ZKSCAN3 elevates migration and invasion abilities through the Akt/mTOR signaling pathway by suppressing p-Akt and p-mTOR expression, thereby promoting proliferation, migration, and invasion." (PMID 39519085, 2024). "Beyond its role in intrinsic apoptosis, ZKSCAN3 also possesses the ability to activate the extrinsic apoptosis pathway, as evidenced by its activation of the Bcl2 signaling pathway and induction of apoptosis in bladder and breast cancer." (PMID 39519085, 2024). "Moreover, a genome-wide association study (GWAS) of breast cancer declared identification of 65 novel loci associated remarkably with a high risk of breast cancer at P < 5 × 10− 8 such as FES, MAP 3 K11, CLK2, GRK7, USP25, DFFA, PKP1, and ZKSCAN3." (PMID 35650591, 2022). "Furthermore, the expression of ZKSCAN3-shRNA profoundly inhibits tumor growth in mice harboring breast cancer xenografts, indicating that suppressing ZKSCAN3 effectively impedes the Akt/mTOR signaling pathway by suppressing the expression of p-Akt and p-mTOR proteins in breast cancer cells." (PMID 39519085, 2024). "Notably, ZKSCAN3 also induced cell death by activating the BCL-2 family-dependent external apoptotic pathway in bladder and breast cancers, suggesting its dual regulatory functions in different cancer types." (PMID 40723888, 2025). "The inhibition of ZKSCAN3 using shRNA in MCF-7 and MDA-MB-231 cells diminishes cell viability, migration, and invasion, highlighting that ZKSCAN3-shRNA significantly decreases the expression of MMP-2, MMP-9, CCND1, and Bcl-2 while augmenting the expression of Bax in breast cancer cells." (PMID 39519085, 2024).
cervical cancer (5 papers, 2018 to 2025). A primary or metastatic malignant neoplasm involving the cervix. "In cervical cancer patients, heightened expression of ZKSCAN3 is linked to reduced overall survival (OS) rates and a higher risk of tumor recurrence." (PMID 39519085, 2024). "In cervical cancer, the oncogenic effect of ZKSCAN3 was found to be further realized through genomic copy number amplification and multidimensional transcriptional reprogramming." (PMID 40723888, 2025). "We carried out quantitative polymerase chain reaction (qPCR) to determine the mRNA expression levels of ZKSCAN3 in four cervical cancer cell lines (C33A, Caski, HeLa and SiHa), along with GM00637, a human fibroblast line, as a control sample." (PMID 30241382, 2018). "Additionally, gene copy number analysis revealed an increased number of ZKSCAN3 copies in cervical cancer samples." (PMID 39519085, 2024). "Notably, in low-grade cervical carcinoma, elevated ZKSCAN3 expression was positively correlated with OS and progression-free survival compared to wild-type cases." (PMID 39519085, 2024). "ZKSCAN3 plays a significant role in cervical cancer progression." (PMID 36012568, 2022).
gastric cancer (3 papers, 2024 to 2025). A primary or metastatic malignant neoplasm involving the stomach. "Elevated ZKSCAN3 expression was associated with both poorer overall survival and disease-free survival among patients with colorectal and gastric cancer, indicating its potential utility as a prognostic marker." (PMID 39519085, 2024). "Clinicopathologic analysis showed that 32.2% of gastric cancer samples had abnormally high expression of ZKSCAN3, and the intensity of its expression was significantly and positively correlated with lymphatic metastasis and distant dissemination." (PMID 40723888, 2025). "The regulatory role of ZKSCAN3 in gastric cancer and its pro-carcinogenic mechanism have been gradually clarified." (PMID 40723888, 2025). "Studies have shown that AP, similar to gastric cancer, suffers from an AlkB homolog 5 (ALKBH5)-mediated demethylation mechanism of ZKSCAN3 mRNA, which leads to the up-regulation of its expression and inhibition of autophagic activity, thus accelerating the development of AP models in mice." (PMID 40723888, 2025). "Prognostic correlation studies have shown that the overall survival (OS) of ZKSCAN3-positive gastric cancer patients was significantly shorter than that of negative patients, indicating its potential application as a biomarker and therapeutic target for evaluating prognosis in gastric cancer." (PMID 40723888, 2025).
Alzheimer disease (2 papers, 2021 to 2025). A progressive, neurodegenerative disease characterized by loss of function and death of nerve cells in several areas of the brain leading to loss of cognitive function such as memory and language. "Recent studies have also shown that PKC activators induce PKC-dependent export of ZKSCAN3 from the nucleus and also promote clearance of amyloid β (Aβ) plaques in mouse models of Alzheimer’s disease." (PMID 34685484, 2021).
colorectal tumor (2 papers, 2018 to 2024). "This suggests that ZKSCAN3 facilitates the progression and infiltration of colorectal tumors, particularly in the presence of CEA-producing tumors." (PMID 39519085, 2024).
liver cancer (2 papers, 2022 to 2025). An epithelial or non-epithelial malignant neoplasm that arises from the liver. "The transcription factor, KLF4 and ZKSCAN3, facilitate ITGB4 expression respectively in glioma and liver cancer by directly binding to its promotor." (PMID 35305660, 2022).
melanoma (2 papers, 2019 to 2020). A malignant, usually aggressive tumor composed of atypical, neoplastic melanocytes. "While our observations do not exclude other reported mechanisms in BRAFi-associated autophagy in melanoma, TFEB/ZKSCAN3 constitutes direct mediators of the autophagy–lysosomal program that affects the responsiveness of melanoma to oncogenic stress." (PMID 30979895, 2019). "Our study indicates that the CAP and SN combination dysregulated autophagy-related genes, including TFEB and ZKSCAN3, which have important functions in connecting BRAF signaling to autophagy-lysosome-mediated catabolism in melanoma." (PMID 32178401, 2020). "We have presented evidence for the inactivation of TFEB and ZKSCAN3 by the co-effect of CAP and SN and blockage of the mTOR/EGFR pathway that provides a compelling model to explain the suppression of melanoma and resultant autophagy-lysosome activation." (PMID 32178401, 2020). "Further, ZKSCAN3 depletion synergized with TFEB overexpression and resulted in growth inhibition of A375 xenograft melanoma." (PMID 30979895, 2019). "Here, the authors describe that BRAF inhibition induces the autophagy-lysosomal function in BRAF-mutant melanomas via modulation of the TFEB and ZKSCAN3 transcriptome, which downregulates TGF-β and suppresses melanoma progression." (PMID 30979895, 2019). "We demonstrate that the BRAFV600E–TFEB/ZKSCAN3–autophagy–lysosomal axis represents a key regulatory pathway through which BRAFV600E orchestrates TGF-β signaling and EMT, resulting in tumor progression, metastasis, and resistance to BRAF-targeted therapy in melanoma." (PMID 30979895, 2019).